CD4 (CD4 molecule)
Diseases named in the same sentence as CD4 in open-access papers (continued):
Sharing a sentence is not in itself a finding about the gene and the disease.
neurosyphilis (continued). "In a previous study, we examined the immune functions of 42 neurosyphilis patients and observed that a cellular immune imbalance and a significant reduction in CD4+ T cells occurred in the white blood cells of neurosyphilis patients." (PMID 29167762, 2017). "A total of 2258 lncRNAs and 1728 mRNAs were identified as over-expressed or under-expressed, respectively (fold change > 1.5) in the CD4+ T cells of neurosyphilis patients compared to the healthy controls." (PMID 29167762, 2017). "Total RNA was isolated using Trizol from CD4+ T cells that were isolated from the neurosyphilis patients and normal controls." (PMID 29167762, 2017). "In our previous study, we found that CD4+ T cells were significantly decreased in neurosyphilis patients." (PMID 29167762, 2017). "In total, 17,278 lncRNAs and 15,840 mRNAs were differentially expressed between the CD4+ T cells of the three neurosyphilis patients and the three healthy control individuals." (PMID 29167762, 2017). "We calculated the positive predictive value of the serum RPR-titre ≥1:32 as well as of the CD4+ cell count for a definite or probable neurosyphilis." (PMID 26445822, 2015). "Considering this we cannot give the advice to use a poor CD4+ cell count or a high RPR-titre to predict a neurosyphilis." (PMID 26445822, 2015). "We therefore analyzed only those 28 patients with available CD4+ cell count and all necessary criteria for the diagnosis of definite or probable neurosyphilis." (PMID 26445822, 2015). "In this study, we observed the CD4+ T cells were accumulated in CSF in neurosyphilis patients, and they were the dominant IL-17-producing cells." (PMID 25080350, 2014). "CD4+ T cells were the predominant cell type in the inflammatory infiltrates in CSF of neurosyphilis patients." (PMID 24244772, 2013). "First, future studies should examine Foxp3 expression and define the functional status of CD4+ CD25high Tregs in CSF in neurosyphilis patients." (PMID 24244772, 2013). "Notably, the patient's HIV infection was in the asymptomatic stage (CD4 count: 262.55 cells/μL), which allowed prioritization of neurosyphilis treatment over immediate ART initiation." (PMID 40860903, 2025). "The third and fourth case vignettes presented a similar patient profile as previous cases with normal CSF cell counts and high protein levels; neurosyphilis treatment was indicated by 57.7% and 75.8% of the respondents for the vignettes with higher and lower CD4+ cell counts, respectively." (PMID 36043668, 2023). "In HIV patients with latent asymptomatic neurosyphilis the CD4 cell count in is usually reduced." (PMID 33225223, 2020). "To date, the roles of lncRNAs in the CD4+ T cell response to Treponema pallidum (T. pallidum) infection in neurosyphilis patients remain unknown." (PMID 29167762, 2017). "Additionally, we observed several differentially expressed mRNAs in the CD4+ T cells of neurosyphilis patients, and their biological functions were investigated." (PMID 29167762, 2017). "In summary, differential lncRNA, and mRNA expression profiles for CD4+ T cells that were acquired from neurosyphilis patients and healthy control subjects were determined, and these data provide a new direction for further research into the pathogenic mechanisms of T. pallidum." (PMID 29167762, 2017). "Recently, neurosyphilis was found to be more prevalent in HIV-infected individuals with high (≥1:32) serum rapid plasma reagin (RPR) titers or low (<350 cells/μL) peripheral blood CD4+ T cell counts, and lumbar puncture was recommended in such individuals." (PMID 28446129, 2017). "We admit that the difference between our results and those suggesting that poor CD4+ T cells or high serum-RPR-titre are predictive for neurosyphilis might be due to the fact that we used other criteria for the definition of neurosyphilis." (PMID 26445822, 2015).
neurosyphilis (continued). "Therefore, we hypothesized that T. pallidum inhibited CD4+ T cell functions through the regulatory effects of lncRNAs on relevant signaling pathways to consequently promote the development of neurosyphilis." (PMID 29167762, 2017). "Some risk factors of neurosyphilis have been reported in HIV-infected individuals, including male sex, higher serum RPR titers and the occurrence of neurological symptoms, as well as profiles of HIV infection (e.g., higher HIV viral load and lower peripheral blood CD4+ T cells)." (PMID 28446129, 2017). "We tried to ascertain whether a poor or good immune status in HIV-coinfected patients, which we defined by a number of CD4+ T cells < or ≥350/μl, increases the risk for neurosyphilis or not." (PMID 26445822, 2015). "Among 128 (77.1 %) of the 166 asymptomatic patients which had CD4+ ≤ 350 cells/mm3 or VDRL titer ≥ 1:32, 15 (11.7 %) had confirmed neurosyphilis: 11 with CSF VDRL positive titers and 4 due to cytologic criteria." (PMID 40157281, 2025). "In contrast, in our cohort, 15 (11.7 %) of the 128 asymptomatic patients with CD4 ≤ 350 cells/mm3 and/or VDRL titers ≥ 1:32 were diagnosed with neurosyphilis." (PMID 40157281, 2025). "Low CD4+ cell count and RPR > 1:32 remain excellent predictors of neurosyphilis, but have become the only acceptable predictors of ANS in PLWH." (PMID 31627294, 2019). "We tried to find other parameters in serum to predict neurosyphilis by using regression analysis for TPPA test, RPR test, IgM-FTA-ABS test, CD4+ cell count, HI-viral-load in serum and HIV-status." (PMID 26445822, 2015). "To investigate the potential role of Th17 in neurosyphilis, we first examined the frequency of IL-17+ among lymphocytes, CD3+, CD4+ T populations in PBMC." (PMID 25080350, 2014). "Interestingly, among these neurosyphilis patients, a significant decrease in CSF CD4+ CD25high Treg percentage and number was observed in symptomatic neurosyphilis patients compared to those of asymptomatic neurosyphilis patients, which may be associated with low CSF TGF-β levels." (PMID 24244772, 2013). "Considering only the 11 patients with CSF VDRL positive titers as having confirmed neurosyphilis, HIV viral load ≤ 400 copies/mm3 (OR = 0.16, 95 % CI 0.031‒0.83, p = 0.029) and CD4 count ≤ 350 cells/mm3 (OR = 10.0, 95 % CI 1.94‒51.21, p = 0.006) were independent risk factors to this outcome." (PMID 40157281, 2025). "The high proportion of HIV-infected patients with low CD4 counts and the high initial serum nontreponemal test titers in our patients are likely to be responsible for the high neurosyphilis rate observed." (PMID 35869241, 2022). "o If the CSF lymphocyte count is between 6–20 cells/μL, but the CD4 count is <200/μL, the patient is receiving antiretroviral (ARV) therapy and the HIV viral load is <50 copies/mL, the patient would be diagnosed with probable neurosyphilis." (PMID 38983560, 2022). "In our previous study, the changes in the lncRNA expression profiles of CD4+ T lymphocytes in neurosyphilis patients and healthy controls were analyzed using a non-coding RNA microarray platform." (PMID 34917045, 2021). "Accordingly, it is possible that if neurosyphilis is more frequent among subjects with CD4 < 350 cells/mm3, this data is not as stringent for patients with ANS who suffer from a less severe condition." (PMID 31627294, 2019). "CD4 cell counts of patients with neurosyphilis and with non-neurosyphilis ranged from 1 to 497 per μL and 1 to 940 per μL, respectively." (PMID 26559304, 2015). "Though we did not elucidate the precise identity of the CD4+ T cell subset, we observed a decreased frequency of CD4+ CD25high Tregs in the CSF of symptomatic neurosyphilis patients compared with those of non-neurosyphilis and asymptomatic neurosyphilis patients." (PMID 24244772, 2013). "Neurosyphilis (NS) is more frequently seen in patients with human immunodeficiency virus (HIV) infection, especially those not on antiretroviral therapy or with a low CD4 cell count." (PMID 31011497, 2019).
osteoarthritis (33 papers, 2014 to 2025). A noninflammatory degenerative joint disease occurring chiefly in older persons, characterized by degeneration of the articular cartilage, hypertrophy of bone at the margins and changes in the synovial membrane. "Both LIGHT mRNA and LIGHT protein have been detected in RA synovial fluid samples and at much higher levels than in synovial fluid from osteoarthritis, and CD4 T cells seem to be a major source of LIGHT in the joints." (PMID 40761796, 2025). "Osteoarthritis (OA) is driven by biomechanical and biochemical inflammatory processes, including CD4+ T cell infiltration and activation." (PMID 40612887, 2025). "The results showed that in osteoarthritis tissues, the levels of T cells CD4 memory resting, Mast cells activated, and NK cells activated were significantly downregulated compared to normal synovial membranes (red part)." (PMID 38549939, 2024). "The results showed that the number of CD8 + T cells and regulatory T cells in osteoarthritis patients was higher than that in the control group, and the number of CD4 + memory T cells was lower than that in the control group." (PMID 38637751, 2024). "Clinical studies have shown that in patients with osteoarthritis (OA), the frequency of CD4+CD25+Foxp3hi Tregs is significantly increased in the peripheral blood compared to healthy controls." (PMID 39364408, 2024). "For example, immune cells such as neutrophils, M1 macrophages, CD4+ T cells, and mast cells have a significant infiltration in OA synovium, suggesting that immune infiltration is a key target for the treatment of osteoarthritis." (PMID 38090564, 2023). "Compared to patients with osteoarthritis (OA) and healthy controls (HC), the percentage of PD‐1+CD4+ T cells in the total T cell population increased significantly in peripheral blood mononuclear cells (PBMC) from patients with RA." (PMID 36509660, 2023). "MiR-204-5p is a newly identified microRNA, which has been elucidated to inhibit synovial fibroblast inflammation in osteoarthritis, and is correlated with CD4+ central memory and effector memory T cell infiltration." (PMID 36474621, 2022). "In agreement with our results, they found elevated levels of several phospho-epitopes in CD4+ T cell subsets in RA patients compared to healthy donors, and, to a lesser degree, to osteoarthritis patients." (PMID 31338093, 2019). "The aim of this study was to determine the effect of MSCs derived from the synovium and bone marrow of osteoarthritis patients on CD4+ T-cells in an allogeneic coculture model." (PMID 27516777, 2016). "In addition, HAVCR2 genetic variations have been linked to increased risk of osteoarthritis, possibly because of upregulation of IFN-γ expression by CD4+ T cells." (PMID 38723011, 2024). "However, the infiltration of γδT cells, resting mast cells and M0 macrophages increased in osteoarthritis synovium tissues while the infiltration of resting memory CD4+ T cells and activated mast cells was reduced." (PMID 36836601, 2023). "In brief, we found four hub genes, i.e., CD4, SELL, ITGB2, and CD52 that are potential diagnostic biomarkers which may contribute to the diagnosis of osteoarthritis and provide further insight into the underlying molecular mechanisms for OA risk genes." (PMID 36468029, 2022). "CD4+ T cell is the T helper cell (Th cell) which may induce inflammation in the early stage of osteoarthritis." (PMID 32189997, 2020). "Adipokines have been shown to induce pro-inflammatory mediators in activated CD4+ T cells from osteoarthritis patients, demonstrating that systemic mediators may play a role in osteoarthritis." (PMID 29527173, 2018). "While we believe that we are the first ones to report on this effect in the context of osteoarthritis, these results match with findings from a number of studies that showed that MSCs could induce FoxP3+ Tregs from the CD4+ fraction." (PMID 27516777, 2016).
osteoarthritis (continued). "SLAMF6 was increased in osteoarthritis and early RA ST, and in circulating early RA PD-1+CD4+ cells and inhibition of SLAMF6 on CD4+PD-1+ peripheral cells from established RA patients decreased IgG production and plasmablast differentiation." (PMID 38077329, 2023). "Meanwhile, q-PCR results of clinical samples showed that four genes (CD4, SELL, ITGB2, and CD52) were upregulated in human primary synoviocytes compared with non-osteoarthritis samples." (PMID 36468029, 2022). "In osteoarthritis, E2F3 is positively correlated with multiple immune cells, including resting mast cells, T regulatory cells, CD4 resting memory T cells and activated NK cells." (PMID 34741389, 2021). "We then compared the infiltration of Th1 cells (IFN-γ+ CD4+), Th17 cells (IL-17+ CD4+), and Th22 cells (IFN-γ− IL-17− IL-22+ CD4+) in synovial tissues from patients with osteoarthritis (OA) and those with RA." (PMID 30619268, 2018). "A similar distribution of CD20:CD3, CD4:CD8, and GATA3:T-bet was seen in perivascular regions in the synovium from patients with osteoarthritis with excessive synovial chronic inflammatory infiltrate." (PMID 25242891, 2014). "For example, elevated miR-146a levels are reported in RA SF and in CD4+ T cells isolated from RA SF, but not in osteoarthritis SF, whereas miR-146a expression in SF CD4+ T cells is positively correlated with SF TNF levels." (PMID 34066338, 2021).
periodontal disease (33 papers, 2010 to 2025). "Through the secretion of cytokines and the activation of osteoclasts, CD4+ T cells are responsible for the inflammation associated with periodontal disease." (PMID 40728992, 2025). "Pro-inflammatory CD4+ T helper cells mainly belong to the Th1, Th2, Th17, and Treg cells, which secrete various cytokines and are closely associated with periodontal diseases." (PMID 35046930, 2021). "A mouse model of alveolar bone loss induced by periodontopathic bacteria Porphyromonas gingivalis showed that CD4+ T cell-derived IFNγ and IL-6 were important effectors of bone loss associated with periodontal disease." (PMID 30158833, 2018). "CD4 levels reported on the records of patients showed a statistically significant association with severity of periodontal disease (p<0.05)." (PMID 27695639, 2015). "CD4 and viral load was statistically associated with bleeding on probing and severe signs of periodontal disease." (PMID 27695639, 2015). "The pR/Kgp::I-Ab tetramer complex will allow the identification of effector/memory CD4+ T cells specific for two virulence factors of P. gingivalis strains associated with periodontal disease." (PMID 23945018, 2013). "Moreover, it has been recognized that an association exists between CD4+ T cell counts and periodontal disease progression." (PMID 23258979, 2012). "Rampant caries and severe periodontal diseases (mean CD4 count, 523±297) might have caused tooth loss and dentures use in some patients with severe immunosuppression, resulting in not being categorized as rampant caries." (PMID 23346337, 2010). "Th17 cells, which originate from CD4+ T cells, have been shown to play a pivotal role in the progression and regulation of periodontal disease, with the cytokines they secrete (mainly IL-17 and IL-22) being a key factor in this process." (PMID 40076898, 2025). "More specifically, necrotizing periodontal disease is associated with patients with HIV‐1 infection experiencing severe immunodeficiency, i.e., a low number of CD4 T lymphocytes, which are the primary target cells of the HIV virus." (PMID 41287475, 2025). "Within the limits of this study, despite the similar periodontal disease severity, a decrease in CD4 + and CD8 + T lymphocyte levels was observed in ACS + P patients compared to P patients." (PMID 38451305, 2024). "It has been reported that human CD4+ T cells are involved in the immune response against oral microorganisms in periodontal diseases." (PMID 35222410, 2022). "This way mTOR pathway impacts the selection and fate of CD4+ T cells which ratify their role in the pathology of periodontal diseases." (PMID 35222410, 2022). "The inflammation in periodontal disease is mediated by CD4+ T cells through cytokine secretion and osteoclastogenetic activity." (PMID 35222410, 2022). "Adapting the local host immune responses, regulated by CD4+ T cells, is a potential mechanism for interfering with the pathogenesis of periodontal diseases." (PMID 35222410, 2022). "It is important to emphasize that, in the pathogenesis of periodontal diseases, CD4+ cells function over other cell types can be dual depending on the cytokines produced." (PMID 32960889, 2020). "It has been reported that during periodontal disease the expression of CD4+, CXCR5+, and CCR5+ is increased; the latter has also been reported increased in smokers." (PMID 31316513, 2019). "Nadir CD4+ T-cell count differentially influences periodontal disease both before and after HAART in HIV-infected adults." (PMID 24146949, 2013). "We found that nadir CD4+ T cell count influences periodontal disease in HIV-infected adults both before and after HAART initiation, and that this influence varies prior to and after HAART initiation." (PMID 24146949, 2013). "The role that different CD4+ T helper cell subsets play in the pathogenesis of periodontal diseases remains unresolved." (PMID 23945018, 2013).